YAP1 (Yes1 associated transcriptional regulator)
Diseases named in the same sentence as YAP1 in open-access papers (continued):
Sharing a sentence is not in itself a finding about the gene and the disease.
cancer (continued). "YAP1/TAZ signaling has recently gained much attention in developmental, cancer and regeneration biology." (PMID 29976931, 2018). "miR-15a inhibits several important genes (BCL2, BMI1, YAP1 and DCLK1), decreasing cancer progression and resistance." (PMID 29416778, 2018). "As the most important effectors, YAP1 and its closely related paralog TAZ act as oncogenes in various human cancers." (PMID 28782275, 2018). "Unphosphorylated YAP1, together with WWTR1, activates the TEAD1-4-mediated transcription in the nucleus, representing the cancer progression accelerator." (PMID 30006603, 2018). "Results of immunostaining revealed morphological changes from a flattened epithelioid appearance to spindle-like fibroblastic morphology in YAP1-depleted WT and LIF+/− cells, resembling that observed in cLIF cancer cells." (PMID 30504771, 2018). "To further validate the role of the β1-integrin-FAK-YAP1/TAZ signaling axis in cancer cell survival and growth on ECM, we treated cancer cells with pharmacological inhibitors PF-228 or verteporfin to target against FAK or YAP1 respectively." (PMID 29872721, 2018). "Given that YAP1 is an oncogene in many cancers, we conclude that miR-16 inhibits the growth and invasion of CCA cells at least partially by targeting YAP1." (PMID 28915618, 2017). "Previous studies showed that cancer features such as cancer stem cell properties, epithelial-mesenchymal transition (EMT), increased migration, and metastasis are regulated by YAP1." (PMID 29340043, 2017). "On a tumorigenesis point of view, YAP1 promotes epithelial-mesenchymal transition (EMT), which is involved in cancer metastasis." (PMID 27835600, 2016). "In support of a dominant function of TEADs in cancer cells, overexpression of an artificial TEAD2-VP16 construct in NIH3T3 cells was reported to mimic the effects of YAP1 overexpression at the transcriptional level and lead to cell transformation." (PMID 26295846, 2015). "YAP1 and TAZ are hyperactivated in many cancers, and therefore considered as promising anti-cancer drug targets." (PMID 26041885, 2015). "In summary, our meta-analysis suggests that the positive YAP1 expression can statistically contribute to poor OS and DFS in patients with carcinoma." (PMID 26263504, 2015). "Therefore, in order to evaluate whether YAP1 sustains the cell proliferation, as suggested by gene expression analyses, we investigated cell growth dynamics in 11q22-amplified cancer cell lines, using the bulk cell populations following sh-mediated stable silencing." (PMID 24810989, 2014). "Next, we used the YAP1/ABHD11‐AS1/STAU2/ZYX/p‐YAP1 signaling pathway as the entry point to explore specific mechanisms via which mechanical signals are conducted from the ECM in ICC cells and their impact on the progression of cancer." (PMID 39703167, 2025). "Collectively, our preclinical study suggests that targeting CDK4/6 could serve as a promising therapeutic approach for treating CRC and other cancers characterized by overexpression of wild‐type DUB3 and YAP1." (PMID 39968498, 2025). "More intriguingly, the stabilization of YAP1 by the CK2α-DUB3 axis could be a common regulatory mechanism in PDAC, CRC, HCC, TNBC and RCC cancer cells." (PMID 39827153, 2025). "We used the YAP1/ABHD11‐AS1/STAU2/ZYX/p‐YAP1 signaling pathway as the entry point to explore the specific mechanisms involved in conduction of mechanical signals from the ECM in ICC cells and their impact on progression of cancer." (PMID 39703167, 2025). "In particular, compared to the untreated group, the extract increased the expression of the tumor suppressor genes LATS2 and PTPN14 in HCT116 cells and decreased the expression of the oncogenes YAP1 and TEAD2 in HT29 cells, suggesting targeted modulation of cancer cell growth." (PMID 41516111, 2025).
cancer (continued). "Thus, four distinct subtypes of SCLC defined by the predominant transcriptional regulatory mechanism operating in cancer cells have been described on the basis of the expression of ASCL1, NEUROD1, YAP1, and POU2F346." (PMID 41290592, 2025). "constructs a novel model of SCLC subtypes defined by differential expression of four key transcription regulators: ASCL1, NeuroD1, YAP1, and POU2F3 according to SCLC primary human tumors, patient-derived xenografts, cancer cell lines, and genetically engineered mouse models." (PMID 40433367, 2025). "This suggests that, in vivo, J54 may also modulate the proliferation of cancer cells, a property that we attributed earlier to the TLK1>NEK1>YAP1 axis that largely affects the contact inhibition features (mechano-transduction) of the cells." (PMID 40227796, 2025). "YAP1 activation, accompanied by decreased LATS2 expression, has been reported in various cancers." (PMID 39247829, 2024). "Co-targeting Yap1 in cancer cells and Cox2 in stroma sensitized PDAC to Gemcitabine treatment and dramatically prolonged survival of mice bearing late-stage PDAC, whereas simultaneously inhibiting Yap1 and Cox2 only in cancer cells was ineffective." (PMID 39468013, 2024). "Consistent with the spatial organization of these FAP+ CAF cluster-related ECT, we observe that cancer cells promote the differentiation of the Detox-iCAF cluster into Wound-myCAF and ECM-myCAF clusters through DPP4- and YAP1-dependent mechanisms both in vitro and in vivo." (PMID 38561380, 2024). "MYL9 can combine with YAP1, a vital regulator of the HIPPO pathway that is crucial for promoting cancer development, especially in CRC, to activate HIPPO signaling and promote the proliferation of cancer cells." (PMID 39768172, 2024). "Single targeting of Yap1 in Panc02 cancer cells or Cox2 in fibroblasts did not enhance Gem response compared to Gem mono-treatment." (PMID 39468013, 2024). "Drugs that currently inhibit the YAP1 protein in GC include verteporfin, metformin, AICAR, and TED-347; however, relatively few studies have been conducted on the potential uses of YAP1-specific inhibitors in cancer." (PMID 38493426, 2024). "Related to YAP1 expression, we identified distinct Hedgehog, Notch, and Wnt signaling pathway signatures in E2 and E3 lytic phenotypes as well as Hippo-independent YAP pathway components reported in cancer." (PMID 39446925, 2024). "Since YAP1 interacted with PRRG2 and was largely required for PRRG2-mediated repression of cancer cell migration and invasion, we mechanistically speculated that PRRG2 likely exerts its metastatic suppressive actions by inhibiting YAP1 activity." (PMID 38355937, 2024). "Moreover, YAP1 can potentially regulate the expression of IL-6 and STAT3, two major drivers of immune evasion and generation of CSCs in human cancers." (PMID 39630608, 2024). "Together these results indicate that, in 14-3-3ζ+++ cancer cells, low-nutrient- or chemotherapy-induced stresses stabilize NLK protein to induce pS128-Yap1 that releases 14-3-3ζ-bound Yap1 for nuclear translocation and activation, leading to CXCL2/5 upregulation." (PMID 39468013, 2024). "As well as being a transcriptional target for YAP/TAZ, NUAK2 was shown to inhibit LATS1 kinase activity, and acute treatment of cancer cells with the dual NUAK inhibitors, WZ4003 or HTH-02-006, increased YAP1S127 phosphorylation and blocked nuclear translocation of YAP1." (PMID 38939918, 2024). "During the formation of cSCC, on the one hand, YAP1 combined with VEGFC to promote lymphatic development and generate anti-cancer cells, and on the other hand, it may combine with TAZ to promote the proliferation of cSCC cells." (PMID 37974224, 2023). "Thus, the direct interaction between cancer cells and fibroblasts induces upregulation of both ZEB1 and YAP1, which in turn promotes a transcriptional reprogramming towards a more aggressive hybrid EMT phenotype." (PMID 36936987, 2023).
cancer (continued). "miR-195 is involved in the regulation of cancer by targeting Cyclin D1, BCL-2, and YAP1." (PMID 38136338, 2023). "Silencing of the CMA receptor LAMP2A increased the levels of both proteins without changes in mRNA expression, and further analysis demonstrated that YAP1 and IL6ST were direct CMA substrates, revealing a novel mechanism that controls the expression of two cancer-relevant proteins." (PMID 35435804, 2023). "Therefore, KRAS dependency is so essential in KRASmu PDAC that cancer cells have secured several compensatory escape mechanisms to counteract the efficacy of KRAS inhibitors, such as activation of MEK/ERK signaling or YAP1 upregulation." (PMID 37298264, 2023). "Since CSCs are implicated in the growth, migration, invasion, angiogenesis, anti-cancer drug resistance, and metastasis in MIBC, the influence of Chaga on the expression levels of three important CSC markers, CD44, SOX2, and YAP1 which were upregulated in most of MIBC were examined." (PMID 37153767, 2023). "The aberrant expression of YAP1 has been identified in CRC and other cancers." (PMID 37793774, 2023). "Currently, no clinically promising drugs are available to target the YAP1-mediated development of cancers, including PC." (PMID 36180487, 2022). "Moreover, TAZ displayed similar clinical significance and oncogenic functions as YAP1 did in EC and was responsible for tribbles pseudokinase 3 (TRIB3)-driven cancer stemness and radioresistance of ESCC." (PMID 36289774, 2022). "Then, we examined the relationship between YAP1 expression and the DFS of patients with cancer." (PMID 35685435, 2022). "The copy number derived expression of 11q22.1-2 amplification resident genes was also observed in a broader cancer context; the TCGA sporadic HNSCC copy number—expression correlation data also showed significant positive correlations, most strongly in YAP1, BIRC2 and TMEM123." (PMID 34997070, 2022). "Although YAP1 and TAZ are believed to be equivalent downstream effectors of the Hippo pathway, differential expression of YAP1 or TAZ suggests distinct functions during cancer progression." (PMID 35930163, 2022). "All these small molecules could inhibit YAP1-driven malignant properties by disrupting TEAD activity, suggesting their potential as candidates for promising cancer therapies." (PMID 36289774, 2022). "Although Hippo pathway is the main upstream regulator of YAP1, mainly by cell contacts, the AKT pathway may become important for cancer cells undergoing EMT." (PMID 35014181, 2022). "The role of YAP1 in CD8+ T cells and MDSCs in other cancer types remains to be unraveled." (PMID 36479120, 2022). "Furthermore, it has been found in sorafenib-resistant HCC that YAP1 can induce an increase in EMT and high expression of IGF-1R, both of which are highly related to cancer stemness." (PMID 35672802, 2022). "Although there are more pathways associated with cancer stem cells and their resistance to therapies, such as Hippo/YAP1, Wnt/ß-catenin, Notch, and JAK/STAT, the main takeaway is that cancer stem cells can resist therapies through quiescence, drug efflux, and anti-apoptosis." (PMID 36176759, 2022). "In the nucleus, YAP1 upregulates genes involved in stemness, cell proliferation, anti-apoptosis, and EMT [[, making it a player in the initiation of cancer and growth of most solid tumors." (PMID 35356283, 2022). "The increase in TAZ expression occurred at both mRNA and protein levels rather than at their stability level in the YAP1-depleted cancer cells." (PMID 35930163, 2022). "In general, YAP1 expression was negatively correlated with its DNA methylation level in most cancer types, suggesting that DNA demethylation in the 5’UTR of YAP1 may promote its expression." (PMID 36479120, 2022). "YAP1 is a pivotal effector that acts as a transcriptional co-activator and is amplified to promote the epithelial to mesenchymal transition (EMT) and malignant transformation in cancers." (PMID 35449153, 2022).
cancer (continued). "CA3, an inhibitor of YAP/TEAD transcriptional activity, inhibits the proliferation and metastasis of other cancers; however, whether it inhibits PAF1-mediated YAP1/TEAD4 transcriptional activity and cancer stem cells in PC is unknown." (PMID 36180487, 2022). "Furthermore, YAP1 and AREG have been reported to be independent prognostic factors for several cancer types." (PMID 35449153, 2022). "Another interesting result in this study is that YAP1 expression was negatively correlated with infiltration of CD8+ T cells, but positively correlated with infiltration of resting CD4+ memory T cells in most cancer types." (PMID 36479120, 2022). "In addition to drug treatment of cells, we also analyzed the protein levels of TAZ, YAP1, and phosphorylated YAP1 (p-YAP1; Ser127) in CCA using the cancer cell line encyclopedia reverse-phase protein array (CCLE_RPPA) database." (PMID 35449153, 2022). "This suggests that, in vivo, J54 may modulate also the proliferation of cancer cells, a property that we attributed earlier to the TLK1 > NEK1 > YAP1 axis, largely affects the contact-inhibition features (mechanotransduction) of the cells." (PMID 36497211, 2022). "The effects of MALAT1 suppression and BET inhibitor JQ1 on the malignant phenotypes and cancer stem cell- (CSC-) like properties of laryngocarcinoma cells as well as the expression of bromodomain-containing protein 4 (BRD4), YAP1, and EMT markers were investigated." (PMID 35601153, 2022). "Invadopodia were scarcely observed in two cancer cell lines (MCF7 and MCF-10A) with YAP1 low expression and T47D cells with YAP1 cytoplasmic retention, and were quite common in MDA-MB-231 and MDA-MB-468 cells with relatively high YAP1 expression and nuclear localization." (PMID 35773411, 2022). "YAP1 interacts with both β-catenin and TBX5 to regulate Survivin expression in cancer cell lines." (PMID 33568044, 2021). "Indeed, increased activity in YAP1 and/or TAZ led to the expansion of CSC populations and cancer progression." (PMID 34959397, 2021). "As the terminal effectors of the Hippo pathway, the transcriptional coactivators YAP1/TAZ and the transcription factors TEAD1–4 present exciting opportunities to pharmacologically modulate the Hippo biology in cancer settings, inflammation and regenerative medicine." (PMID 34685695, 2021). "We observed increased YAP1 and TAZ mRNA, and protein suggesting the progression of cancer." (PMID 33795755, 2021). "Overexpression of the YAP1 target genes, including CTGF and Cyr61, is actively involved in cell proliferation, reprogramming, stemness, EMT, anti-apoptosis, and chemoresistance acquisition in cancer cells." (PMID 34743733, 2021). "In cancer cells, the negative regulatory role of AMPK could be uncoupled by unknown mechanisms, leading to hyperactivation of the YAP1 pathway." (PMID 34462427, 2021). "The transcription of YAP1 and TAZ in the Hippo signaling pathway plays a critical role in mediating the resistance of major cancer treatment drugs, and is considered to play a major driving role in the development of resistance of BRAF- and KRAS- mutant cancer cells." (PMID 33996543, 2021). "It is intriguing that the apoptosis inhibitor BCL2 is among the target genes of YAP1, a fact that could contribute to YAP1 dependency in 20q11.21 amplified cancers, given that the related BCL2L1 protein is dysregulated in these cancers." (PMID 34577783, 2021). "Interestingly, YAP1 has been shown to be involved in both oncogenic KRAS-dependent and KRAS-independent cancer-promoting activities." (PMID 34094936, 2021). "Aberrant YAP1 and AGK expressions have been reported in various human cancers." (PMID 32827244, 2020). "As YAP1 was strongly associated with a positive ERG status, it is not surprising that YAP1 was either positively or inversely related to most deletions when all cancers were jointly analyzed." (PMID 32488048, 2020).
cancer (continued). "Even though YAP1 activity on increasing cell proliferation and inhibiting apoptosis justifies its high level of expression and function in several cancer types, this is not the only way that YAP affects the persistence and survival of cancer cells." (PMID 32722184, 2020). "However, in our study, the activation of YAP1 by CPE promoted cell proliferation, invasion ability, stemness, EMT, and consequent cancer malignancy." (PMID 32064037, 2020). "Although serine phosphorylation is the first trigger required for YAP1 nuclear export, the inhibition of SFK activity by dasatinib in cancer related fibroblasts (CAFs) reduces the YAP1 nuclear localization leading to a higher citoplasmic content resembling normal fibroblasts." (PMID 32290470, 2020). "However, the contribution of IL-13/STAT6 and YAP1, together with serum AFP, are proven to have the upper hand in predicting cancer development in NASH." (PMID 32283835, 2020). "It was proposed that Yap1 physically interacts with HIF1α with in cultured cancer cell lines, whereas HIF2α was shown was shown to enhance Yap1 activity without direct interaction of the two proteins." (PMID 31958058, 2020). "YAP1 and TAZ are overexpressed in many primary tumors and increased nuclear staining of these proteins has been reported as a prognostic marker for poor survival in several types of cancer." (PMID 32218280, 2020). "Although it is not clear how YAP1 is deregulated in cancer, emerging evidence suggests that the YAP protein functions as an oncogene in tumorigenesis." (PMID 33260691, 2020). "TEADi could potentially be used to dissect the TEAD-dependent and independent roles of YAP1/TAZ signaling and aid in the discovery of improved targeting strategies for this pathway in cancer and other pathologies." (PMID 32193376, 2020). "Often, both nuclear and cytoplasmic YAP1 staining of cancer cells did not unequivocally differ from the staining in normal prostate glands in our study." (PMID 32488048, 2020). "For both nuclear and cytoplasmic staining, these analyses revealed that YAP1 staining is linked to deletions of 8p and PTEN (10q) in both ERG positive and ERG negative cancers (p ≤ 0.0004 each)." (PMID 32488048, 2020). "The roles of the Hippo signaling pathway and its effectors YAP1 and WWTR1 in cancer immunity remains unclear." (PMID 32990596, 2020). "Because YAP1 expression was also linked to a positive ERG status, it was not surprising to find that high nuclear and cytoplasmic YAP1 staining was linked to deletions of 8p, 10q (PTEN), 16q and 17p (p < 0.0001) if all cancers were jointly analysed." (PMID 32488048, 2020). "High YAP1 nuclear expression correlates with poor patient outcome in EAC and some other cancers." (PMID 32175692, 2020). "Although several ongoing clinical trials are now evaluating the efficacy of verteporfin as a photosensitizer in different types of cancers, none have declared the intent to evaluate YAP1-inhibitory effects." (PMID 31137841, 2019). "We speculate that miR-375 may fulfill regulatory drug resistance function in the majority of malignant cancer cells, whereas it seems to be blurry about how miR-375 modulates the therapeutic resistance of CRC cells by targeting YAP1." (PMID 31543507, 2019). "We found negative correlation between YAP1 nuclear and cytoplasmic immunoreactivity levels in cancer cells (r = −0.32, p = 0.0166)." (PMID 29850494, 2018). "Multiple studies have now reported that Yap1 can function independent of the Hippo pathway, and it has further been shown that Yap1 is a direct phosphorylation target of Src in a number of cancer cell lines, independent of the canonical Hippo pathway." (PMID 30322398, 2018). "Curiously, cancer-associated, activating mutations of YAP/TAZ have not been found, and YAP1 and TAZ genes are rarely amplified in cancer cells." (PMID 30101371, 2018).